PIK3CA (phosphatidylinositol-4,5-bisphosphate 3-kinase catalytic subunit alpha)
Diseases named in the same sentence as PIK3CA in open-access papers (continued):
Sharing a sentence is not in itself a finding about the gene and the disease.
tumor (continued). "PIK3CA and NT5E expression levels were also significantly elevated in tumor-positive compared with tumor-free samples." (PMID 41209574, 2025). "NGS performed on tumor tissue or liquid biopsy in metastatic disease is essential for comprehensive molecular profiling, including ESR1 and PIK3CA gene assessments, among others." (PMID 39935426, 2025). "In this context, miRNAs inhibiting expression of PTEN (miR-425 and miR-148a) should be considered as oncomirs, and those inhibiting KRAS, EGFR, PIK3CA, TGFBR1, and SMAD2 (let-7g, miR-150, miR-128, miR-139, miR-148a, miR-148b) as tumor suppressors." (PMID 40868120, 2025). "In the present case, characterized by a rare HCC profile with PIK3CA positivity and PYGO2 negativity, the molecular profile suggests an aggressive tumor phenotype driven by activation of the PI3K signaling axis." (PMID 41133538, 2025). "Given the potential role of PI3K in tumor progression, PI3K inhibition has emerged as a promising therapeutic strategy in PIK3CA-mutant breast AS." (PMID 40666093, 2025). "Promising activity (42% DCR); highest responses in tumors with PIK3CA/PTEN aberrations; well tolerated; supports further tumor‐ and biomarker‐specific trials." (PMID 40740483, 2025). "In ECs specifically, alpelisib demonstrated efficacy in reducing tumor burden in patients with coexisting PTEN and PIK3CA alterations." (PMID 39858102, 2025). "Notably, we observed a high mutation frequency of PIK3CA in CRC samples based on the mutation profiles of ICD-associated genes, suggesting that PIK3CA mutations may influence CRC growth and progression via DAMPs, by altering the tumor’s immune response." (PMID 40257955, 2025). "In PIK3CA-mutant xenografts (e.g., engineered MCF-7/H1047R models), combination therapy produced marked tumor growth inhibition and extended tumor doubling times relative to monotherapy." (PMID 41280894, 2025). "Among these, PTEN mutations have been reported in up to 55–80% of endometrioid endometrial tumors and their precursor lesions, while PIK3CA and ARID1A often co-occur in endometrial neoplasms, contributing to tumor progression." (PMID 40227624, 2025). "From the WES of the patient’s original tumor, we identified the KRAS and PIK3CA driver genes, which were reported to be frequently observed in MLA." (PMID 41311737, 2025). "Similar tumor cell killing results were observed with the two PIK3CAN345K-specific TCRs, which showed much higher avidity to the mutant PIK3CA peptide." (PMID 41410746, 2025). "Testing for PIK3CA/AKT1/PTEN alterations was carried out using FoundationOne®CDx, a tumor tissue-based next-generation sequencing (NGS) test, for all patients except those enrolled in China, where OncoScreen Plus® was used instead." (PMID 40597213, 2025).
tumor (continued). "This requires glucose uptake and energy sources for normal cellular response to stress and tumor growth, syndrome development, vascular changes, and megalocephaly (e.g., PIK3R1; PIK3CA; PIK3CG; PIK3CD; PIK3CB; PIK3R3; PIK3R2; PIK3R5; PIK3R6)." (PMID 41010006, 2025). "In this particular case of PIK3CA-positive and PYGO2-negative HCC, we should expect an aggressive tumor with PI3K pathway activation." (PMID 41133538, 2025). "Mechanistically, we demonstrated here that the combination of CB-839 and 5-FU induced IL-8 expression in PIK3CA-mutant CRC cells, thereby attracting neutrophils into the tumor tissues." (PMID 38194275, 2024). "In conclusion, our study demonstrated that RNA-seq and microarrays showed similar performance in predicting clinical endpoints, except for a few genes such as PIK3CA and BAX in certain tumor types." (PMID 38463169, 2024). "Against this backdrop, the PIK3CA gene emerges as a key player in TNBC's aggressive phenotype, potentially influencing tumor tropism through the modulation of complex signaling pathways." (PMID 39369580, 2024). "PIK3CA, a linchpin in the PI3K/AKT/mTOR pathway, significantly influences tumor tropism by modulating chemokines, growth factors, and extracellular matrix (ECM) interactions." (PMID 39369580, 2024). "Similarly, the use of NGS to identify a PIK3CA missense mutation in a patient without a definitive pathological diagnosis of cutaneous malignancy has allowed targeted treatment of an otherwise complex tumor with uncertain histology." (PMID 39659799, 2024). "Other factors involve tumor gene expression profiles like microRNA patterns, NRF2, PIK3CA and distinct gene expression classifiers." (PMID 39085866, 2024). "Multiregion sequencing of the primary tumor and metastatic sites revealed differences in the genomic profiling, including oncogene amplifications such as EGFR, ERBB2, MET and PIK3CA." (PMID 38611014, 2024). "For example, cancer RNA biomarkers such as KRAS, PCA3, PIK3CA mutants, EGFRvIII, FOLH1, KLK2, KLK3, EML4-ALK, and NYP have been reported to be sequestered by platelets that actively uptake tumor-derived material." (PMID 39274207, 2024). "More recently, high-p21 levels were shown to promote tumor growth and resistance to HER2-targeted therapies in HER2 and PIK3CA mutant breast cancers." (PMID 38273040, 2024). "In the TGFβ pathway, co-occurring mutations were found in SMAD2 and SMAD3 (FDR-adjusted P = 1.03 × 10−10) in nHM tumours, whereas TGIF1 co-occurred with PIK3CA (FDR-adjusted P = 0.09) in the HM cases." (PMID 39112715, 2024). "PIK3CA amplifications were found in ~2% (n = 3) of patients including two patients with HR+/HER2- MBCs and one patient with a TNBC tumour." (PMID 39322687, 2024).
tumor (continued). "Phosphatidylinositol-4,5-Bisphosphate 3-Kinase Catalytic Subunit Alpha (PIK3CA) activation enhances the expression of downstream PI3K-Akt pathway genes, inhibiting apoptosis and promoting tumor development." (PMID 39445058, 2024). "Longer treatment of PIK3CA, PTEN altered gastric cancer models suggests that paclitaxel treated tumour had small increased activation of AKT, however, the mechanistic interactions, and shorter time points were not explored." (PMID 38396173, 2024). "The present study correlates the expression levels of critical genes (PIK3CA, PTEN, AKT1, FOXO1, and FRAP) in 60 tumor tissues with clinicopathological and demographic characteristics." (PMID 38891994, 2024). "The detection of EGFR and PIK3CA amplifications in patients HN03 and HN06 illustrates the dynamic nature of tumor evolution and the development of resistance under ICI therapy." (PMID 39796090, 2024). "It is reported that the overexpression of c-Met occurs in about 20–25% of patients with NSCLC and persistently stimulates PIK3CA, MAPK, and STAT pathways to bypass EGFR, thereby inducing the malignant progression of the tumor." (PMID 39468027, 2024). "In the context of previous research, our findings align with studies highlighting the role of PIK3CA and EP300 in tumor progression and VM formation." (PMID 39165361, 2024). "Occasionally, vacuolated tumour areas could be observed, which is indicative of lipid accumulation inside the cells, while being much less pronounced when compared to our phosphatidylinositol-4,5-bisphosphate 3-kinase catalytic subunit alpha (PIK3CA) injection model." (PMID 37946160, 2023). "Levels of miRNA-10b-5p, PIK3CA, p-PI3K as well as p-AKT were found to be enhanced in the tumor tissues." (PMID 37568787, 2023). "The effect of XIN-10 and GDC-0941 on the expression of PIK3CA(p110) and mTOR1 in transplanted tumors was examined by PCR experiments on MCF-7 transplanted tumor tissues from nude mice." (PMID 37834269, 2023). "The cyclin pathway, as well as altered downstream signalling pathways involving genes like PIK3CA and PTEN, can encourage tumour growth." (PMID 37711177, 2023). "These patients were compared to a group of 54 patients (included in the 1200 initially screened patients, with available tumor exome) with ER+/HER2− tumors, but with PIK3CA-WT status." (PMID 36934165, 2023). "Candidate tumor-agnostic molecular targets in the three gynecological malignancies included ERBB2, PIK3CA, ARID1A, and KRAS." (PMID 38201563, 2023). "While in this model PI3K pathway deregulation alone is insufficient for tumor development, concurrent RU486-induced PIK3CA overexpression and 4NQO administration results in over 40% of tumors exhibiting increased invasion and metastasis." (PMID 37474617, 2023). "Its tumor suppressor function is more well researched, with ARID1A inactivation resulting in tumor initiation in PTEN- or PIK3CA-mutant cells in gynecological malignancies and hypermutated/MSI-type cells in colon cancer." (PMID 37109525, 2023).
tumor (continued). "Patients with KRAS, NRAS, PIK3CA and BRAF wild-type tumours were randomised between the pan-HER inhibitor AZD8931 and placebo." (PMID 35256486, 2023). "Additionally, PI3K, AKT, and mammalian target of rapamycin (mTOR) inhibitors may serve as potential therapeutic options for patients with PIK3CA and PTEN mutations, whereas an mTOR inhibitor can be used as a therapeutic approach for targeting STK11- and FBXW7-deficient tumours." (PMID 38024139, 2023). "PIK3CA coexisted with only two of the four ARID1A mutant cases, and it would be interesting to further study the codependency of these two genes in tumor formation." (PMID 37465112, 2023). "Two patients received long‐term TMZ chemotherapy before surgery, and mutations in the SHh (PTCH1) and PI3K/AKT signaling pathways (AKT1, PIK3CA, PTPN11) were detected in two tumor tissues (Patients 24 and 27)." (PMID 37533228, 2023). "Overactivation of PIK3CA and loss of activity of PTEN due to the double mutations can lead to hyperactivation of PI3K/Akt/mTOR signaling which may result in oncogene induced senescence (OIS), potentially explaining the blockage of tumor growth in the double mutant X-3093 xenograft." (PMID 36808143, 2023). "In this regard, they discovered that one tumor clone exhibited EGFR, CDK6, and MET amplification, whereas another subclone received a copy of chromosome 3 with PIK3CA, resulting in PIK3CA amplification." (PMID 37762559, 2023). "Overall, the inhibition of PIK3CA and mTOR1 expression in MCF-7 transplanted tumor tissues was stronger in the GDC-0941 treatment group than in the XIN-10 treatment group, which was consistent with the results of tumor suppression rate of the compounds." (PMID 37834269, 2023). "Common tumor-suppressive microRNA, miR-375, directly targets PI3K (PIK3CA) in CRC, while miR-92 exhibits oncogenic activity through the inhibition of a set of tumor-suppressors, including PTEN." (PMID 36013453, 2022). "Clear answers will require large phase 3 studies, and results from the CAPItello-291 trial in which NGS is used to identify PIK3CA, AKT1, and PTEN tumour alterations are eagerly awaited." (PMID 35671774, 2022).
tumor (continued). "Indeed, the identification of the second mutation in the PIK3CA gene, not detected in the primary tumor, could be interpreted as disease progression." (PMID 35682999, 2022). "Half of the tumors (50%) carried at least one molecular alteration that is targetable in other tumor types, including alterations in CDKN2A (6.0% biallelically inactivated), ERBB2 (9.3%) and PIK3CA (10%)." (PMID 36335173, 2022). "ER-negative tumor amplifications were also focused on ERBB2 with less frequent amplifications of AKT1, CDKN1B, FOXO3, GATA3, KRAS, PIK3CA and TBL1XR1." (PMID 36140723, 2022). "The PFS median (the primary endpoint) was 5.9 months with capivasertib, and 4.2 with the placebo; in patients with PIK3CA/AKT/PTEN, the altered tumours PFS median was 9.3 months with capivasertib vs. 3.7 months with the placebo (HR 0.30)." (PMID 35954393, 2022). "Baicalein inhibits PIK3CA by downregulating the expression of BDLNR, and ultimately blocked the PI3K/AKT signaling and thus inhibited the growth of ovarian cancer in tumor-bearing mice." (PMID 36232344, 2022). "Mice with HCC70-Mut PIK3CA tumors and treated with TCR4 had a significant reduction in tumor volumes and enhanced survival compared to mice that received the Flu-specific TCR or PBS controls." (PMID 35484264, 2022). "We and others have recently demonstrated that CUL4B regulates the expression of several tumor suppressors, including MYCN, PIK3CA, HER2, SOX4, C-MYC and CDH2 at the posttranscriptional level." (PMID 35784474, 2022). "It has been reported to inhibit the growth of a variety of cancers, particularly in PIK3CA mutant and KRAS wild-type tumor cells." (PMID 35392233, 2022). "Increasing rigidity promotes tumor formation and can induce resistance to therapies targeting mTORC1, HER2, and/or PIK3CA." (PMID 35884439, 2022). "Three tumor samples (T5, T16, and T19) exhibited high-level amplification in 3q26, including WWTR1, TP63, PIK3CA, SOX2, SOX2-OT, and ZNF639 genes." (PMID 34285259, 2021).